HMGA1P8 (high mobility group AT-hook 1 pseudogene 8)
Synonyms: HMGA1-p
Gene: Processed pseudogene on chromosome 2 (74,418,122 to 74,418,442, reverse strand). Ensembl gene ENSG00000233155.
Diseases named in the same sentence as HMGA1P8 in open-access papers:
HMGA1P8 is named in the same sentence as 3 diseases in open-access papers, as found by Europe PMC text mining. Sharing a sentence is not in itself a finding about the gene and the disease.
HMGA1P8 shares sentences with these, for which no sentence is quoted: anaplastic thyroid carcinoma (1 paper); cancer (1); tumours (1).